DHTKD1 (dehydrogenase E1 and transketolase domain containing 1)
Description:
2-oxoadipate dehydrogenase (E1a) component of the 2-oxoadipate dehydrogenase complex (OADHC). Participates in the first step, rate limiting for the overall conversion of 2-oxoadipate (alpha-ketoadipate) to glutaryl-CoA and CO(2) catalyzed by the whole OADHC. Catalyzes the irreversible decarboxylation of 2-oxoadipate via the thiamine diphosphate (ThDP) cofactor and subsequent transfer of the decarboxylated acyl intermediate on an oxidized dihydrolipoyl group that is covalently amidated to the E2 enzyme (dihydrolipoyllysine-residue succinyltransferase or DLST) (Probable). Can catalyze the decarboxylation of 2-oxoglutarate in vitro, but at a much lower rate than 2-oxoadipate. Responsible for the last step of L-lysine, L-hydroxylysine and L-tryptophan catabolism with the common product being 2-oxoadipate (Probable).
Synonyms: E1a; OADC-E1; OADH-E1; KIAA1630; MGC3090; DKFZP762M115; CMT2Q; AAKAD; AMOXAD
Tractability: Small molecule: a structure with a bound ligand is known. PROTAC: ubiquitination databases record sites on it; its protein half-life has been measured.
Gene: Protein-coding gene on chromosome 10 (12,068,926 to 12,123,225, forward strand). Ensembl gene ENSG00000181192.
Subcellular location: Mitochondrion
Subcellular location (Human Protein Atlas): Mitochondria
Pathways (Reactome):
Metabolism: OADH complex synthesizes glutaryl-CoA from 2-OA
Gene Ontology:
Molecular function: 2-oxoadipate dehydrogenase activity; protein binding; oxidoreductase activity, acting on the aldehyde or oxo group of donors, disulfide as acceptor; thiamine pyrophosphate binding
Biological process: generation of precursor metabolites and energy; amino acid catabolic process; L-lysine catabolic process
Cellular component: mitochondrion; oxoadipate dehydrogenase complex; mitochondrial matrix
Genetic constraint (gnomAD): Loss-of-function variants: 64 observed, 91.25 expected, observed/expected ratio (o/e) 0.7, 90% interval 0.57 to 0.86. The upper end of that interval is the gene's LOEUF score, 0.86, which puts it in group 3 of 6, group 1 being the genes least tolerant of losing a copy. Missense variants: 1,109 observed, 1,111.8 expected, observed/expected ratio (o/e) 1, 90% interval 0.95 to 1.05. Synonymous variants: 430 observed, 435.84 expected, observed/expected ratio (o/e) 0.99, 90% interval 0.91 to 1.07.
Gene-disease validity (ClinGen):
ClinGen rates the evidence that DHTKD1 causes each of these diseases.
2-aminoadipic 2-oxoadipic aciduria (autosomal recessive): Definitive.
Homologues: Orthologues: chimpanzee DHTKD1 (99% identical), macaque SEC61A2 (97% identical), dog DHTKD1 (91% identical), rabbit DHTKD1 (90% identical), rat Dhtkd1 (88% identical), guinea pig DHTKD1 (88% identical), mouse Dhtkd1 (88% identical), pig DHTKD1 (84% identical), tropical clawed frog dhtkd1 (76% identical), zebrafish dhtkd1 (71% identical), Caenorhabditis elegans ogdh-2 (49% identical), Drosophila melanogaster CG1544 (48% identical). Paralogues in human: OGDHL (39% identical), OGDH (39% identical).
Diseases named in the same sentence as DHTKD1 in open-access papers:
DHTKD1 is named in the same sentence as 102 diseases in open-access papers, as found by Europe PMC text mining. Sharing a sentence is not in itself a finding about the gene and the disease. The quoted sentences say what the papers report.
breast carcinoma (16 papers, 2011 to 2025). "In breast carcinoma, differential DNA methylation between tumors and normal tissues was found correlated with the expression level of DHTKD1." (PMID 34827193, 2021).
glioma (10 papers, 2009 to 2021). A benign or malignant brain and spinal cord tumor that arises from glial cells (astrocytes, oligodendrocytes, ependymal cells). "The C6 rat glioma and MCF-7 human breast adenocarcinoma cell lines are similar to tissues with relatively low and high DHTKD1 level, respectively." (PMID 32024885, 2020).
melanoma (10 papers, 2010 to 2025). A malignant, usually aggressive tumor composed of atypical, neoplastic melanocytes. "In melanoma cells, the loss of GCDH triggers cell death programs that can be prevented by inhibiting DHTKD1." (PMID 40896397, 2025). "Moreover, knockdown of GCDH in melanoma cells led to the activation of cell death programs, which could be prevented by inhibiting the upstream lysine catabolism enzyme DHTKD1." (PMID 40896397, 2025).
bladder cancer (6 papers, 2014 to 2025). "Exons 2 and 16 of DHTKD1 transcripts were back-spliced to develop circDHTKD1 that can promote lymphatic metastasis of bladder cancer by upregulating CXCL5." (PMID 38139387, 2023).
diabetes (5 papers, 2018 to 2021). "Impaired mitochondrial energy metabolism is linked to development of diabetes and obesity, however whether impairments in DHTKD1 function predispose to the development of diabetes, obesity and cardiometabolic disease through modulation of mitochondrial energy metabolism remains to be determined." (PMID 34484123, 2021). "Thus, the synthesis and specific action of the OADH inhibitor AP, characterized in this work, provide a useful tool for deciphering cell-specific molecular mechanisms which underlie the known associations between the DHTKD1 expression with diabetes, obesity and cancer." (PMID 32024885, 2020). "Human genetic data further highlight the relevance of DHTKD1 in diabetes and cardiometabolic disease." (PMID 34484123, 2021). "Moreover, pharmacological tools to specifically affect the OADH function may be of therapeutic significance, as regulation of the DHTKD1 expression is observed in a number of pathological conditions, including diabetes, obesity and malignant transformation." (PMID 33511099, 2020). "Remarkably, ∼50% of these protein-coding genes were also DE following anti-diabetes drug-treatment; including ALDH6A DHTKD1, PCYT2 and RND3 (this compares with <5% of the transcriptome responding to drug -treatment)." (PMID 29986096, 2018).
Charcot-Marie-Tooth disease (3 papers, 2021 to 2023). An inherited degenerative disorder involving the peripheral nerves. "Nevertheless, decreased mitochondrial function and increased reactive oxygen species are observed in epithelial cells of patients with allergic inflammation of esophageal epithelium or Charcot-Marie-Tooth disease, where the DHTKD1 mutations are enriched." (PMID 35721081, 2022). "In human Mendelian disorders, mutations in DHTKD1 have been linked to 2-Aminoadipic, 2-Ketoadipic, and 2-Oxoadipic Aciduria, as well as Charcot-Marie-Tooth Disease." (PMID 34484123, 2021). "The DHTKD1 mutations are often associated with muscle weakness and Charcot-Marie-Tooth disease." (PMID 35721081, 2022). "This review considers the enzymes encoded by the DHTKD1, PDK3 and PDXK genes, whose mutations are observed in patients with Charcot-Marie-Tooth (CMT) disease." (PMID 37508330, 2023). "However, this same mouse model has been used as a model of Charcot Marie Tooth disease, where higher serum insulin was reported in Dhtkd1 -/- mice compared with WT in both the fasted and re-fed state." (PMID 34484123, 2021).
eosinophilic esophagitis (3 papers, 2021 to 2023). Eosinophilic esophagitis (EoE) is a chronic, allergic disease of the esophagus characterized clinically by symptoms of esophageal dysfunction (including vomiting, dysphagia, feeding disorders, food impaction and abdominal pain) which persist after treatment with proton pump inhibitors (PPIs). "Genetic findings have linked the DHTKD1 encoding 2-oxoadipate dehydrogenase (E1a), the first component of the OADHc, to pathogenesis of AMOXAD, eosinophilic esophagitis (EoE), and several neurodegenerative diseases." (PMID 35897808, 2022). "Genetic studies have linked variants in DHTKD1 to the (neuro) pathogenesis of several metabolic disorders: α-aminoadipic and α-ketoadipic aciduria (AMOXAD: MIM 204750), Charcot-Marie-Tooth disease type 2Q (CMT2Q: MIM 615025) and eosinophilic esophagitis (EoE), a chronic allergic disorder." (PMID 33946784, 2021).
Obesity (3 papers, 2020 to 2021). Accumulation of substantial excess body fat. "Ability of adipoyl phosphonate to specifically regulate the DHTKD1-encoded protein in vivo may be useful to develop combinatorial therapies correcting pathological states associated with changed DHTKD1 expression, among which are insulin resistance, obesity, and cancer." (PMID 32024885, 2020). "Disruption of the Dhtkd1-2-AAA pathway in mice associates with inflammation, obesity and metabolic phenotypes." (PMID 34484123, 2021).
amyotrophic lateral sclerosis (2 papers, 2021 to 2022). Amyotrophic lateral sclerosis (ALS) is a neurodegenerative disease characterized by progressive muscular paralysis reflecting degeneration of motor neurons in the primary motor cortex, corticospinal tracts, brainstem and spinal cord. "Rare heterozygous DHTKD1 encoded DHTKD1 variants were recently identified in patients with amyotrophic lateral sclerosis (ALS), a progressive neurodegenerative disorder." (PMID 35897808, 2022).
cognitive delay (2 papers, 2021 to 2025). "The phenotype of individuals with DHTKD1 gene variants ranges from asymptomatic to severe intellectual disability, muscular hypotonia, developmental delay, ataxia, and epilepsy." (PMID 39038845, 2025).
Insulin resistance (2 papers, 2018 to 2020). Increased resistance towards insulin, that is, diminished effectiveness of insulin in reducing blood glucose levels. "Lack of GM-CSF driven myeloid cells lead to reduced adipose tissue 2-oxoglutarate dehydrogenase complex (DHTKD1) levels and subsequent increase in plasma 2-aminoadipate (2-AA) levels, both of which are reported to correlate with insulin resistance." (PMID 30065264, 2018). "The global removal of GM-CSF leads to increased adiposity, profound reduction in adipose tissue GM-CSF driven myeloid cells, that is accompanied with an increase in DHTKD1 levels, lower plasma 2-AA levels, and protection from diet-induced insulin resistance." (PMID 30065264, 2018).
Type 2 Diabetes (2 papers, 2021 to 2025). "Common variants in DHTKD1 associate with Type 2 Diabetes and cardiometabolic traits in large genome-wide associations studies." (PMID 34484123, 2021). "Genome-wide association data confirmed a strong association between SNPs in the DHTKD1 region and Type 2 Diabetes, in addition to glucose and HbA1c." (PMID 34484123, 2021). "Notably, DHTKD1 is also associated with type 2 diabetes, and it has been reported that 6‐oxo‐PIP is significantly elevated in adult type 2 diabetes patients." (PMID 39038845, 2025).
Coronary Artery Disease (1 paper, 2021). "We also observed an association with Coronary Artery Disease, suggesting that the effects of disruption in DHTKD1 function may affect overall risk of cardiometabolic disease." (PMID 34484123, 2021).
frontotemporal dementia (1 paper, 2023). Frontotemporal dementia (FTD) comprises a group of neurodegenerative disorders, characterized by progressive changes in behavior, executive dysfunction and language impairment, as a result of degeneration of the medial prefrontal and frontoinsular cortices. "The DHTKD1 gene causes not only ALS, but also CMT2 and SMA, and ALS-frontotemporal dementia may be associated with DYNC1H1 mutation." (PMID 36882741, 2023).
liver steatosis (1 paper, 2021). "Dhtkd1 possibly modulates mitochondrial biogenesis, enhances energy expenditure to control liver steatosis, and is acted upon by LNC_000204, LNC_000150, ENSMUST00000144661.2, and ENSMUST00000181906.1." (PMID 34368149, 2021).
microcephaly (1 paper, 2023). A congenital or acquired developmental disorder in which the circumference of the head is smaller than normal for the person's age and sex. "Variants in OGDH, OGDHL, and DHTKD1 isoenzymes have been associated with various clinical phenotypes, including microcephaly." (PMID 38031187, 2023).
spinal muscular atrophy (1 paper, 2021). A motor neuron disease that affect the muscles, and characterized by muscle weakness and atrophy resulting from progressive degeneration and irreversible loss of the anterior horn cells in the spinal cord (i.e., lower motor neurons) and the brain stem nuclei. "Thus, variants in the DHTKD1 gene encoding dehydrogenase E1 and transketolase domain containing 1 previously linked to 2-aminoadipic and 2-oxoadipic aciduria, Charcot-Marie-Tooth (CMT) disease type 2, and spinal muscular atrophy (SMA) were identified." (PMID 35052424, 2021).
tumor (269 papers, 2003 to 2026). "DHTKD1 was found interacting with the tumor suppressive miR-29 family members." (PMID 34827193, 2021).
metabolic disorder (3 papers, 2021). "The severe effects of Dhtkd1 knockout on motor and neurological function in mice may make this an inappropriate model for the study of metabolic disease." (PMID 34484123, 2021). "Taken together, these data strongly suggest that DHTKD1 plays a pivotal role in cell metabolism and may be an important regulator linking the 2-AAA pathway to metabolic disease." (PMID 34484123, 2021).
neurological disorders (2 papers, 2023 to 2024). "Interestingly, OGDH, OGDHL, and DHTKD1 each possess a ThDP binding domain, and thiamine (vitamin B1) administration is an intriguing treatment possibility, as oral thiamine has been used to improve various neurological disorders with minimal adverse reactions." (PMID 38031187, 2023).
neurodevelopmental disorder (1 paper, 2023). A behavioral and cognitive disorder with onset during the developmental period that involves impaired or aberrant development of intellectual, motor, or social functions. "Going further, we uncovered evidence for a complex compensatory relationship among OGDH, OGDHL, and DHTKD1 isoenzymes that are associated with neurodevelopmental disorders and exhibit complex transcriptional compensation patterns with partial functional redundancy." (PMID 38031187, 2023).
DHTKD1 also shares sentences with these, for which no sentence is quoted: infection (158 papers); cancer (130); viral infection (33); adenovirus infection (20); prostate carcinoma (13); hepatocellular carcinoma (10); ovarian carcinoma (9); pancreatic cancer (9); lung carcinoma (8); colon carcinoma (6); gastric cancer (5); bladder tumor (3); colorectal cancer (3); glioblastoma (3); liver cancer (3); lung adenocarcinoma (3); brain cancer (2); brain tumour (2); cervical carcinoma (2); mesothelioma (2); metastatic tumor (2); neuroblastoma (2); prostate tumors (2); renal carcinoma (2); retinoblastoma (2); skin cancer (2); AIDS (1); aneuploidy (1); Ataxia (1); axonal motor neuropathy (1).
A further 51 diseases each share a sentence with DHTKD1 in 1 paper.